TGFB1 (transforming growth factor beta 1)
Diseases named in the same sentence as TGFB1 in open-access papers (continued):
Sharing a sentence is not in itself a finding about the gene and the disease.
metastatic disease (106 papers, 2002 to 2026). "We analyzed the association of genetic polymorphisms in TGFB1 with clinicopathological characteristics and prognosis in patients with non-metastatic disease." (PMID 34113577, 2021). "We also noted a similar association between TGFB1 expression and clinical outcome when considering both primary and metastatic tumors in the TCGA dataset." (PMID 28448494, 2017). "All four gene sets implicated TGFβ1 as an important upstream regulator that suppresses metastatic disease (p = 3.7x10-3–9.3x10-18), consistent with the role of TGFβ in early tumor progression." (PMID 27074153, 2016). "Furthermore, there have been reports of significant association between plasma TGFβ1 and overall survival in patients with locally advanced metastatic disease, Smad 4 loss correlation with lower survival with potential important implications in treatment decision." (PMID 23125850, 2012). "In RCC the TGFβ1 expression levels can be correlated with tumor stage, being the TGFβ1 levels significantly elevated in RCC patients with metastatic disease." (PMID 25909813, 2014). "Recent studies have shown that TGFB1 is associated with poor prognosis and risk of progression in metastatic prostate cancer patients but not in non-metastatic disease." (PMID 38441550, 2024). "Conversely, the level of TGFβ1 decreased after calcitriol treatment in CAFs from metastatic tumors." (PMID 38360633, 2024). "Consequently, in the simulations TGFβ1 production was maintained consistent between primary and metastatic tumors, on the same order of magnitude as the baseline value in18." (PMID 31636296, 2019). "TGFβ-1, CXCR4, BMP1, VCAN, and WNT2 are more expressed in original tumors compared to metastatic tumors, according to the data." (PMID 41348904, 2025). "We looked at the TGFβ-1, CXCR4, BMP1, VCAN, and WNT2 expression profiles in a few BC datasets related to primary and metastatic tumors." (PMID 41348904, 2025). "This was corroborated with increased gene expression of EMT markers such as TGFβ1, CDH2 and Snail correlating with higher Gleason score and/or metastatic tumor colonies in sites other than the tumors in prostate." (PMID 31360736, 2019). "In conclusion, this study showed that TGFB1 genetic variations were associated with adverse characteristics and risk of progression during ADT among patients with metastatic disease, but not those with non-metastatic disease." (PMID 34113577, 2021). "Finally, we analyzed the impact of TGFB1 genotype on survival between patients with non-metastatic and metastatic diseases." (PMID 34113577, 2021). "TGFB1 genetic variations were associated with adverse characteristics and progression risk in ADT among patients with metastatic disease, but not those with non-metastatic disease, supporting a distinct role of TGF-β signaling between non-metastatic and metastatic prostate cancer." (PMID 34113577, 2021). "Since TGF-β1 has been suggested to play a dual role in the early and later stages of cancer development, the differential impact of TGFB1 genotype on non-metastatic and metastatic diseases may be explained by the distinct biological role of TGF-β signaling according to tumor stage." (PMID 34113577, 2021).
atrial fibrillation (105 papers, 2012 to 2026). A disorder characterized by an electrocardiographic finding of a supraventricular arrhythmia characterized by the replacement of consistent P waves by rapid oscillations or fibrillatory waves that vary in size, shape and timing and are accompanied by an irregular ventricular response. "For example, in a model of atrial fibrillation, nicotine treated atrial fibroblasts demonstrated reduced levels of miR-133, increased expression of Tgfb1 and its downstream target Ctgf, as well as higher levels of collagen production and atrial fibrosis." (PMID 30427927, 2018). "A cohort study including paroxysmal (<7 days) versus persistent (>7 days) atrial fibrillation patients proved that altered expression of TGFβ1, MMP-9, and tissue inhibitor of metalloproteinase-1 (TIMP-1) plays a vital role during fibrosis progression, whereas IL-6 contributes to inflammation events." (PMID 37569677, 2023). "This is relevant since transgenic mice expressing a constitutively active form of TGFβ1 were shown to develop atrial but not ventricular fibrosis and had increased susceptibility to atrial fibrillation." (PMID 28720711, 2017). "Indeed, Spp1−/− or Ccr2−/− mice showed attenuated atrial fibrillation while macrophage OPN was identified as a mediator of TGFβ1-dependent inflammatory and profibrotic activation of atrial fibroblasts, both in the mouse model and in atrial fibrillation biopsies." (PMID 39595580, 2024). "TRPM7 is markedly upregulated in atrial fibrillation (AF) patients, activating the calcineurin pathway and producing a synergistic effect with TGFβ1, and resulting in the activation of fibroblasts." (PMID 35359592, 2022). "Through induction of transforming growth factor beta 1 and MMP-9 (associated with myocardial matrix remodeling) and induction of myocardial fibrosis, hypoxia-inducible factor 1α and Ang II are associated with pathogenesis and maintenance of atrial fibrillation (AF)." (PMID 33855053, 2021). "In mice, TGFβ1 overexpression resulted in atrial fibrosis, without ventricular involvement, and these mice developed inducible atrial fibrillation (AF)." (PMID 26883434, 2016).
osteoporosis (103 papers, 2009 to 2026). A condition of reduced bone mass, with decreased cortical thickness and a decrease in the number and size of the trabeculae of cancellous bone (but normal chemical composition), resulting in increased fracture incidence. "A patient with a c.945G>C mutation in the TGFB1 gene, associated with Kamurati-Engelman disease, had moderate osteoporosis along with muscle pain syndrome." (PMID 35052464, 2022). "By degrading TRAF3 in MPCs, TGFβ1 promotes increased resorption and decreased bone formation, implicating it in the pathogenesis of low-level chronic inflammation-related osteoporosis." (PMID 36631487, 2023). "The osteoporosis candidate genes transforming growth beta 1 (TGFB1) and estrogen receptor alpha (ESR1) are both localized within this locus." (PMID 21818327, 2011). "Therefore, we can conclude that CWH has suppressive activity on post-menopausal osteoporosis via the induction of Wnt and TGFβ1 signaling." (PMID 39861108, 2025). "Furthermore, genetic predisposition to osteoporosis (the VDR, COLIAI, COLIA2, and TGFB1 gene variants) can affect thalassemia trait complications." (PMID 39062234, 2024). "We propose that pharmacologic reduction of TGFβ1+CCR5+ neutrophil numbers in BM could treat or prevent age-related osteoporosis." (PMID 36631487, 2023). "Despite these advances, the major sources of TGFβ1 in inflammaging-induced osteoporosis remain unknown." (PMID 36631487, 2023). "However, few researches have been conducted to expose the integrated role of miR‐497, leucine‐rich alpha‐2‐glycoprotein‐1 (LRG1) and transforming growth factor beta 1 (TGF‐β1)/Smads signalling pathway in osteoporosis." (PMID 32975015, 2020).
lupus (101 papers, 2006 to 2026). "To assess whether Tgfb1 deficiency in macrophages promotes DN T-cell formation in our findings in lupus-prone mice, we backcrossed Lyz2cre+Tgfb1fl/fl mice to B6.lpr mice." (PMID 32503973, 2020). "Specifically, ligand–receptor pairs such as Thy1-(Itgam+Itgb2), Mif-(Cd74+Cxcr4), Tgfb1-(Tgfbr1+Tgfbr2), and Pecam1-Pecam1 showed higher mean expression levels in lupus mice than in DHA-treated mice." (PMID 40728997, 2025). "Other promising urine biomarkers—such as Angptl4, L-selectin, TPP1, and TGFβ1—also had high ROC AUC values for distinguishing patients with lupus and AR from those with iSLE, with the combination of Angptl4, L-selectin, and TPP1 yielding the highest discrimination with an AUC of 0.97." (PMID 38673612, 2024). "Thus, TGFβ1 production from MZMs restricts the development of DN T cells in lupus-prone mice which results in reduced autoimmune manifestations." (PMID 32503973, 2020).
renal cell carcinoma (101 papers, 2012 to 2025). "For example, in renal cell carcinoma, ARID1A-deficient cells showed decreased apoptosis and increased TGF-β1 (Transforming Growth Factor beta 1) protein expression, which promoted metastasis and epithelial–mesenchymal transition." (PMID 40429787, 2025). "As for the regulated targets in the renal cell carcinoma pathway, TGFB1, EPAS1, HIF1A, VEGFA, KRAS, and PIK3CA regulated by miR-140 have been reported to interfere with KIRC." (PMID 35528546, 2022). "Of note, in previous studies, TGFB1 has been found to enhance proliferative and metastatic potential by upregulating lymphoid enhancer-binding factor 1 and integrin αMβ2 in human renal cell carcinoma, and PVRL2 has been found to be induced in cancer and to suppress CD8+ T lymphocyte function." (PMID 35860689, 2022). "Thus changes in expression levels of EGF and TGFB1 in renal cells might modulate the renal cell carcinoma (RCC) development, in consequence of changes in regulatory elements of signaling networks such as the microRNAs (miRNAs)." (PMID 25909813, 2014). "CCL22, CRP, ICAM1, IFNG, PDGFRA, TGFB1 and TNFSF11 have been confirmed to be involved in the malignant progression and metastasis of renal cell carcinoma through different biological mechanisms." (PMID 34187413, 2021). "In breast cancer and renal cell carcinoma (RCC) autocrine signaling by CSF-1R was demonstrated in vivo and was modulated by TGFb1 and EGF, respectively." (PMID 27486763, 2016). "Furthermore, YBX1 promotes the translation of TGFβ1 mRNA in proximal tubule cells, and knocking down YBX1 reduces the downstream signaling molecules of TGFβ1 in renal cell carcinoma." (PMID 38255791, 2024). "It was previously reported that TGFβ1 upregulation after CD151 silencing could revive malignancy, suggesting that CD151 may promote renal cell carcinoma partially by regulating TGFβ1 amounts and inducing TGFβ1/Smad signaling." (PMID 33767593, 2021).
periodontitis (96 papers, 2013 to 2026). An acute or chronic inflammatory process that affects the tissues that surround and support the teeth. "The dissociation of which is proposed to be induced by increases in ROS (caused by PBM), to form active TGFβ, of which there are three mammalian isoforms where TGFβ1 has been identified as a periodontitis biomarker." (PMID 33991267, 2021). "Additional research on periodontitis has documented alterations in various inflammatory biomarkers, including an upregulation of endothelin-1, transforming growth factor-beta 1, and vascular endothelial growth factor." (PMID 39074834, 2024). "TGFB1 was previously correlated to chronic periodontitis, its importance lies in the fact that this growth factor stimulate tissue remodeling and wound healing through increasing fibroblast proliferation, angiogenesis, and extracellular matrix production, and by inhibiting MMPs." (PMID 32814559, 2020). "Interestingly, our recent study has shown that periodontal TGFβ1 expression is increased in patients with periodontitis." (PMID 26581717, 2015). "Therefore, it is likely that TGFβ1 plays a role in the downregulation of periodontal CD14 expression in patients with periodontitis." (PMID 26581717, 2015). "Taken together, our findings suggest that decitabine inhibits bone resorption in mice with periodontitis by upregulating KLF2 expression and thereby enhancing the expression of IL10 and TGFβ1." (PMID 33671221, 2021). "Other authors, in a study focused on the relationship ανβ6 integrin-periodontitis, took into consideration the involvement of TSP1 in periodontal disease via MMPs and TGFβ-1, with the involvement of TSP1 in activation of TGF 1β being already shown." (PMID 24967433, 2014).
psoriasis (94 papers, 2011 to 2026). An autoimmune condition characterized by red, well-delineated plaques with silvery scales that are usually on the extensor surfaces and scalp. "miR-31 has been shown to be regulated by transforming growth factor beta 1 (TGF-β1), a cytokine associated with psoriasis." (PMID 26362816, 2015). "In addition there was a significant influx of plasmacytoid and dermal dendritic cells into the skin following TGFβ1 induction, and pDCs have been strongly linked to the initiation of chronic inflammation in psoriasis." (PMID 23326666, 2012). "When compared to psoriasis, TGFB1 expression in keratinocytes was markedly lower or even absent in AD." (PMID 37391412, 2023). "TGFb1 has an important role in psoriasis: Increased epidermal and serum TGFb1 levels correlate with disease severity, and mouse models with keratinocyte‐specific human TGFb1 overexpression (K5.hTGFb1wt) recapitulate the human disease." (PMID 37226685, 2023). "In patients with psoriasis, TGFβ-1 induces the generation of FOXP3 positive Treg cells in the absence of IL-6 and the production of Th-17 cells in the presence of IL-6." (PMID 30744173, 2019). "Importantly, these include IL‐6, IL‐21, and TGFb1 cytokines that have been shown to contribute to Th17 differentiation, a T cell subtype that marks psoriasis." (PMID 36855912, 2023). "A representative proinflammatory cytokine, IL-18, has been classified as a biomarker for the activity of psoriasis, in addition to other cytokines including transforming growth factor beta 1 (TGF-β1), tissue inhibitor of metalloproteinase 1 (TIMP-1), and matrix metalloproteinase 1 (MMP-1)." (PMID 26901187, 2016). "“Vascular endothelial growth factor” (VEGF-) transgenic mice, “endothelial specific receptor tyrosine kinase” (K5-Tie2-) transgenic mice, and “transforming growth factor beta 1” (K5-TGFb1-) transgenic mice are psoriasis animal models that highlight the importance of angiogenesis in this pathology." (PMID 26136626, 2015). "The psoriasis-like inflammation that develops in TGFβ1 overexpressing mice however does not appear dependent on T cells or the IL17/IL23 axis." (PMID 23326666, 2012).
aortic aneurysm (90 papers, 2007 to 2025). A ruptured aneurysm located in the wall of the proximal portion of the descending aorta proceeding from the arch of the aorta. "TGFB1, as a cytokine, participates in a broad range of cellular regulatory processes and associated with different kinds of diseases including aortic aneurysm." (PMID 35307021, 2022). "Since dysregulation of the Hif-1α/Vegfa and Tgfb1/Ctgf pathways has been linked to aortic aneurysm progression, these Nox4 target genes likely contribute to aortic pathology in PKG1RQ/+ mice." (PMID 31387997, 2019). "The results of TNFα and TGFβ1 determinations obtained in this study are associated with the thickening and high disorganization of the structure of elastic lamella in the aortic aneurysm of MFS patients." (PMID 29483877, 2018). "Our results show that TGFβ1 and TNFα concentrations in the homogenized tissue from the aortic aneurysm the MFS patients were increased, and this increase was associated with accumulation of collagen, cystic necrosis and degradation of elastic fibers as observed in the photomicrographs." (PMID 29483877, 2018). "Interestingly, the AKT pathway, a nonclassical pathway downstream of TGFβ1, is implicated in the development of aortic aneurysms." (PMID 39742002, 2024).
malaria (88 papers, 2005 to 2025). Malaria is a serious and sometimes fatal disease caused by a parasite that commonly infects a certain type of mosquito which feeds on humans. "In the present study, the SNPs of the two host genes involved in immune functions, i.e., TGFβ1 and IL10, and the one involved in malaria parasite binding (ICAM1) were significantly associated with P. falciparum parasitemia." (PMID 34698295, 2021). "Gene network analysis of TGFB1/IL-6 or IL-17-related gene expression after malaria infection also suggested that malaria was TH17 dependent." (PMID 24188121, 2013). "Furthermore, the same network identified KEGG terms related with protozoan infection, such as malaria, Chagas disease and leishmaniosis, pointing to a convergent set of genes (TGFB1, TGFB3, and TGFBR2) related with those infections and BV." (PMID 36985125, 2023). "The genes involved in host immune response and binding of the malaria parasite, particularly TGFβ1, IL10 and ICAM1 may play a more significant role in malaria parasitemia in P. falciparum than in P. vivax infection." (PMID 34698295, 2021). "For instance, increased plasma levels of pro-inflammatory tumour necrosis factor (TNF), interferon-gamma (IFN-γ), and interleukin-1 beta (IL-1β), as well as decreased levels of anti-inflammatory cytokines, such as IL-10 and transforming growth factor beta 1 (TGF-β1), are hallmarks of severe malaria." (PMID 27357958, 2016). "Six genes (TGFB1, CD36, THBS1, FABP1, PCK1, and IRS1) were involved with malaria, PPAR signaling, and the adipocytokine signaling pathway." (PMID 36193307, 2022). "Among them, malaria, PPAR signaling, and the adipocytokine signaling pathway reached statistical significance (FDR value of <1 and p < 0.05) and included TGFB1, CD36, THBS1, FABP1, PCK1, and IRS1." (PMID 36193307, 2022). "In contrast, gene networks centred on TGFB1/IL6, IL-17, or IFN-αβ were more dramatically altered during the malaria disease cycle." (PMID 24188121, 2013). "Indeed, defects in the production of TGF-β (TGFB1) and IL10, two anti-inflammatory factors, are associated with acute, severe malaria, severe malaria anemia, and an overall negative outcome." (PMID 33123155, 2020).
liver cirrhosis (85 papers, 2006 to 2025). "In rat model of thioacetamide-induced liver cirrhosis, removal of the spleen promotes a significant decrease in blood levels of Tgfb1, which is beneficial for the liver repair." (PMID 32531779, 2020). "In summary, we found that miR-27a was significantly up-regulated in the serum of HBC patients, DMN-induced rat liver cirrhosis and TGFβ1-activated HSCs." (PMID 29416678, 2018). "The objective of this study was to determine the roles of transforming growth factor β (TGFβ1), metalloproteinase-2 (MMP2), collagen αI (Collα1) and tissue inhibitor of metalloproteinase-1 (TIMP1) in preventing thioacetamide-induced liver cirrhosis in rats." (PMID 23829630, 2013). "In addition, the study also discovered the expression of GCA, GCDCA and TCDCA induced TGFβ1 in vitro hepatic stellate cells (HSCs), which indicated that primary conjugated bile acid is related to HSC activation and fibrosis in liver cirrhosis." (PMID 39164750, 2024).